IL6 (interleukin 6)
Diseases named in the same sentence as IL6 in open-access papers (continued):
Sharing a sentence is not in itself a finding about the gene and the disease.
infection (continued). "Comparing the groups with mild infection, we found that only IL-6 was significantly higher in RSV patients versus HRV patients and dual (RSV/HRV) infected patients, indicating that IL-6 was related to the virus and not to the severity of infection." (PMID 26426613, 2015). "This may suggest that IL-6 and TNF-α in the sera at the later part of infection was mostly contributed by DV NS1 protein activating TLR6." (PMID 26226614, 2015). "At first, the expression level of a typical inflammatory cytokine, IL-6 in lung homogenates was evaluated using ELISA, and it was found that IL-6 production was significantly lower in LG2055-administered mice at 5 days after the PR8 infection." (PMID 24717726, 2014). "In BEAS-2B cells at 10 h of infection, IRF-7, ISG15 and Mx1 expression were significantly down-regulated (p<0.05) while STING expression was significantly up-regulated (p<0.05); expression of IFN-β and IL-6 was unchanged." (PMID 25313647, 2014). "Notably, A549 cells showed significantly higher expression of IFN-β and IL-6 expression than BEAS-2B and NHBE cells at 10 h of infection." (PMID 25313647, 2014). "We observed that IFN-γ, TNF-α, IL-6 but not IL-10 production was increased initially 18 hours post-infection and decreased gradually thereafter following treatments with AMP and AZM." (PMID 24565171, 2014). "We did not perform any further studies on IL6 as IL6 was not significantly up-regulated at 7 days post infection when the cells were brought to ALI to differentiate and was therefore unlikely to affect epithelial composition." (PMID 25033192, 2014). "Results suggest that heat-killed C. neoformans increased the expression levels of IFN-I, IL-1β and IL-6 in the acute phase of infection and enhanced IL-17A production after 2 h (data not shown)." (PMID 24660033, 2014). "The comparative analysis between the primary and secondary infections and the noninfected controls revealed significant differences for IL-6, IL-17, and IL-10." (PMID 25295285, 2014). "From the results presented here, it is not possible to conclude if infection is responsible for the IL-1β, IL-6, or IL-4 cytokine production, or if other environmental or genetic differences are responsible for individual differences in cytokine levels." (PMID 24548288, 2014). "However, children with heavy S. haematobium infections had significantly higher GMI of urinary IL-6 (p < 0.001) and lower GMI of urinary IL-10 (p = 0.002) than children with light infections." (PMID 25223302, 2014). "Previously we and others have shown that a variety of cytokines and chemokines were induced by both HRV 14 and/or HRV 16 infection in vitro that include FGF-Basic, chemokines and cytokines like IL-6, IL-15, MCP-2, IP-10, MIP-1β, type I IFN-α, type III IFN-λ2 (IL-28A), and ENA-78." (PMID 25500821, 2014). "In particular, the expression pattern that we observe for IL6, in which non-survivors are significantly more up-regulated in early stages of infection than survivors, is supported by similar changes in protein concentration reported in previous studies." (PMID 25079789, 2014). "Immunity was not due to lower proportions of Th17 cells in the MLN in mice lacking IL-6, as these mice were able to generate significantly increased proportions of Th17 cells equivalent to the level of WT mice following infection." (PMID 24185641, 2014). "Cytokine storm is characterized by abundant release of pro-inflammatory cytokines, such as IFN-γ, TNF-α and IL-6, as well as the anti-inflammatory cytokines such as IL-10; however, its mechanism of induction in oriential infection is not totally understood." (PMID 25254971, 2014). "Also, this result was in contrast with a previous study in which TLR3−/− mice showed reduced cytokine (e.g., TNF-α and IL-6) responses, BBB permeability, neuroinvasion, and mortality following infection with mammalian cell-passaged WNV." (PMID 25188232, 2014).
infection (continued). "Primary genital C. suis infection of the re-infection group (nine-week-old pigs) resulted in increased secretion of TNF-α, IL-1β, IL-6 and IL-12p40 by PBMC, whereas primo-infection of the infection group (seventeen-week-old animals) decreased the IL-1β, IL-8 and IL-10 secretion by PBMC." (PMID 25252649, 2014). "However, A/H7N9-infected C57BL/6 mice exhibited higher levels of IL-6, MCP-1, and IL-1β, but lower levels of TNF-α and IFN-γ, than A/H7N9-infected BALB/c mice at day 3 postviral infection." (PMID 24676272, 2014). "After infection of CMH5 with PRU, at 8 h post infection, we observed a non-significant synthesis for interleukins (IL-6 and IL-8), chemokines (MCP-1, MIF and GROα), growth factors (G-CSF and GM-CSF) and SERPIN E1." (PMID 24886982, 2014). "Mice immunized with IB010 had significantly lower post-infection tissue bacterial loads and significantly lower serum levels of the pro-inflammatory cytokines IL-1β, TNF-α and IL-6 compared to control mice in a mouse model of disseminated A. baumannii infection." (PMID 25485716, 2014). "A detailed measurement of levels of 23 cytokines in the BAL, at 2-day intervals between days-0 to 25 revealed maximal elevation of inflammatory cytokines IL1a, IL1b, IL6, TNFα, IFNγas well as chemokines mKC, Eotaxin, MIP1a, MIP1b and MCP1 during the days 5–9 of infection (Fig-1A & Fig-S1)." (PMID 24505273, 2014). "Unlike IL-1β, IL-8, and TNFα, IL-6 transcription was significantly up-regulated 8 h after infection." (PMID 24712747, 2014). "This is further supported by the lack of induction of IL6 and IL1β, major NFkβ targets, whose expression was significantly repressed during infection with Mtb-H rather than Mtb-A." (PMID 24743303, 2014). "TNF-α, IFN-γ, IL-6 are cytokines important for mounting a proper adaptive antiviral response to HSV-2, while CCL2 can attract monocytes and T cells to the site of infection." (PMID 25117537, 2014). "The authors were able to demonstrate that IL-1 and IL-6 were significantly increased in synovial fluids from patients with PJI compared with patients without infection, with an AUC of above 0.9." (PMID 24586496, 2014). "IL-6 and IL-8 (data not shown) mRNAs were also up-regulated in response to the infection in NPTr cells at 8 and 24 hpi but not in PAMs." (PMID 24712747, 2014). "Investigations into the cytokine response of naïve fibroblasts to infection with N. caninum found that, after 72 hrs, there was a striking and significant increase in production of IL-6, IL-1β but not TGF-β1." (PMID 24961164, 2014). "Notably, the expression intensity of Foxp3 was significantly lower in naïve IL-6−/− compared with that in BALB/c mice, while the disparity between the strains narrowed following infection." (PMID 24185641, 2014). "As was observed at 24 h, IL-6 was elevated in CPEfat/fat mice 48 h post-infection but this difference was not statistically significant." (PMID 25203099, 2014). "Similarly, we observed up-regulation of IL-6, IL-1β and TNF-α in OA hOBs at peak infection (24 hpi) in our study." (PMID 25407789, 2014). "The presence of 33 nm AgNPs at infection led to significantly up-regulated TNF-α, IL-10, CCL2 and down-regulated IL-6 production (p≤0.05), while 46 nm AgNPs significantly down-regulated TNF-α and IL-6 (p≤0.05)." (PMID 25117537, 2014). "Although the difference is not significant, serum levels of IL-6 in mice infected with ΔspxA2 are obviously higher than in WT-infected mice at 6 h post infection." (PMID 25264876, 2014). "To confirm these previous observations, we measured circulating levels of IL-6 and IL-4 in a small cohort of IgAN patients and controls, all without clinical signs of infection for at least 4 weeks before sampling." (PMID 24398680, 2014). "Although the number of patients with severe CDI was limited, we noted a significant association of severe disease with elevations in circulating eotaxin, IL-6, and IL-8 levels compared with non-severe infection." (PMID 24643077, 2014).
infection (continued). "These authors could not found any differences between groups in other markers of infection such as WCC, CRP, IL-6 and body temperature." (PMID 25132018, 2014). "Similar observations could be made for other routine infection and inflammation markers such as C-reactive protein (CRP), procalcitonin (PCT), IL-6, and sCD14-ST." (PMID 25498125, 2014). "The increased lethality appeared to result from an elevation in key pro-inflammatory cytokines and chemokines, such as IL-6, IFNγ and MCP-1; whilst in the latter phase of the infection, Socs4R108X/R108X mice displayed impaired trafficking of virus-specific CD8 T cells to the lungs." (PMID 24809749, 2014). "Production of IL-6 and MCP-1 triggered by infection with parental bacteria peaked at day 3 p.i.." (PMID 24904838, 2014). "Monolayer infection of S. Typhimurium N-15 in the presence of low Fe or high Fe fermentation effluents did not change cytokines expression of IL-1β, IL-6 or IL-8 compared to normal Fe effluent." (PMID 24676135, 2014). "Based upon these data, we speculate that the suppression of TLR7/8-mediated TNF-α and IL-6 expression by MSC-conditioned medium modulates the pathogenesis of ssRNA virus infection, including infection by influenza virus." (PMID 24191131, 2013). "No significant modulation of IL-6 production in serum was obtained either post-infection or post-vaccination." (PMID 23398967, 2013). "Among the four groups (i.e., non-infection group, LTBI group, TB at diagnosis group, and TB under treatment group), inflammatory cytokines, including IL-6, TNF-alpha, and IFN-gamma decreased from the non-infection group to the LTBI group, and then increased in the TB patients." (PMID 23356448, 2013). "We then measured the production of IL-6 and MMP-3, one and three days post-infection." (PMID 24116215, 2013). "At day 68 post-infection (35 days post-treatment), higher levels of IL-6 were detected in footpads of infected non-treated mice (P<0.01), as compared with mycobacteriophage D29 treated mice (P<0.05)." (PMID 23638204, 2013). "The accumulation of Il-6 mRNA was increased in lungs of Socs3fl/fl lck cre M. tuberculosis-infected mice at 4 but not at 2.5 weeks after infection compared to controls." (PMID 23853585, 2013). "Surprisingly, we find that the presence of the interaction with E-cadherin does not affect the infection rate but modulates slightly the IL-6 release and in a more pronounced manner the CCL2 secretion." (PMID 23460827, 2013). "IL-6 was detectable in uninfected colonic tissue; the increase upon infection was however not as marked as that seen for IL-8 and IL-1β." (PMID 23922820, 2013). "Tnf mRNA and protein levels were reduced in M. tuberculosis- or BCG-infected gp130F/F BMM and were partially restored in gp130F/F Il-6−/− BMM, indicating that SOCS3 allows proper infection-induced TNF secretion in macrophages by hampering gp130/IL-6 receptor-mediated signalling." (PMID 23853585, 2013). "It was recently reported that infection of murine monocytic cells with an influenza virus lacking PB1-F2 (ΔPB1-F2) induced higher levels of IL-6 and IL-1β than with the wt virus." (PMID 23704945, 2013). "At 1 dpi, a statistical difference in the upregulation of interleukin-4 (IL-4), interleukin-6 (IL-6), tumor necrosis factor (TNF), and interferon-γ (IFNγ) was observed between NiV-M and NiV-B infections, with higher expression of these genes in response to NiV-M." (PMID 23342177, 2013). "During infection, SIGNR3 is expressed in lung phagocytes and interacts with Mtb bacilli and mycobacterial surface glycoconjugates and mediates host protection by inducing secretion of protective cytokines including TNFα and IL-6." (PMID 24350246, 2013). "On the other hand, when cPLA2 was blocked 1 h before the infection by treatment of macrophages with cPLA2 antagonist ATK (gray bars), proinflammatory cytokines TNF-α, IL-1β, and IL-6 were upregulated; furthermore, IL-10 expression was significantly affected when cPLA2 was inhibited." (PMID 23555077, 2013).
infection (continued). "We observed enhanced IFN-β induction by Vaccinia Virus at 8 hours post-infection, although we were not able to detect IL-6 at this time point." (PMID 23853595, 2013). "Therefore, prior to examining de novo transcription of iron-sequestering genes during infection we first quantified the number of neutrophils infiltrating C57BL/6 and IL-6−/− infected corneas by flow cytometry using the Ly6G NIMP-R14 monoclonal antibody." (PMID 23853581, 2013). "The number of regulated genes declined at 48 h post infection to 5.4% and increased again in the chronically infected cells to constitute 10.1% of the genes in this category, with a modified spectrum of highly induced genes, namely IL3RA, IL6, IL24 and SPRY4." (PMID 23326599, 2013). "Like CRP, both the infected and non-infected neonates showed a significant increase of IL-6 when compared to the control neonates at all time intervals indicating that it is increased both in infection and inflammation." (PMID 23869218, 2013). "In contrast, ultraviolet-irradiated RV14 did not increase the expression of IL-1β, IL-6, and IL-8 at any time point after infection." (PMID 24303127, 2013). "In addition, inflammatory cytokines such as IL-1β, IL-6, and TNF-α activate coagulation systems in infection, trauma, inflammation, and cancer." (PMID 23874602, 2013). "IL-6 has also the highest sensitivity (89%) and negative predictive value (91%) at the onset of infection compared with other biochemical markers, including CRP, TNF, and E-selectin." (PMID 24570828, 2013). "Therefore, we evaluate the levels of BAL and serum IL-6, IFN-β and TNF-α on day 2 post-infection and the concentrations of IFN-γ and IL-10 on day 5 after challenge." (PMID 23947615, 2013). "The IL-6 levels in supernatants from Socs3fl/fl lck cre and Socs3fl/fl lung cells obtained 2.5 weeks after infection, stimulated or not with PPD, were similar." (PMID 23853585, 2013). "Only IL-1β, IL-6, TNF and IL-4 were significantly induced by infection in the spleen (the latter also in the liver), while the production of IL-12p70 and IL-13 decreased with infection, in the liver." (PMID 23459556, 2013). "Infection with neither the pilD or pilC1 mutant strain resulted in any detectable expression of human IL-6 or IL-8, suggesting tfp mediated adhesion is crucial for this endothelial signaling." (PMID 23359320, 2013). "Significantly less induction of pro-inflammatory cytokines, TNF-α, IL-6, IL-1β and MCP-1, was found at various time post-infection in ApoE−/− mice; whereas anti-inflammatory cytokine IL-10 was not affected, and IL-12 production was not detectable during infection." (PMID 23977160, 2013). "IL-6 concentrations after CPXV-GER1991-3 or CPXV-FIN2000-MAN exposure were similar to those of uninfected animals (p>0.05) whereas increased levels were seen (p = 0.0179) following CPXV-BR, CPXV-AUS1999-867 or CPXV-GER1980-EP4 infection." (PMID 23457480, 2013). "DC activation was further confirmed by IL-6 and TNF-α secretion upon EV1 infection." (PMID 23638101, 2013). "For the cytokines FGF basic and IL-15 the addition of PBMCs did not significantly change the levels and for IL-6 the addition of PBMCs did not affect the relative differences between the levels associated with HRV 14 and HRV 16 infection." (PMID 23799120, 2013). "The spleen of Ank1Ity16/ity16 mutant mice appeared to be underresponsive to infection-induced cytokines as measured by very little or no induction of Il1 and Il6." (PMID 23390527, 2013).
infection (continued). "Lack of stimulation of IL-6 expression has previously been seen with the host-specific serovar S. Gallinarum in a comparison to S. Typhimurium and S. Enteritidis after infection of a primary chicken cell line." (PMID 23530934, 2013). "IL-6 expression was not significantly upregulated in either infection group on day 3 p.i. but was highly significantly upregulated on day 7 p.i. in response to lethal infection than nonlethal infection." (PMID 23526993, 2013). "Therefore, cell culture supernatants collected at 24 h post infection were analyzed for the presence of MCP-1, IL-8, IL-6, GM-CSF, and soluble cell adhesion molecules (ICAM-1, VCAM-1, and E-selectin)." (PMID 24069284, 2013). "However, the infection group had significantly higher PCT (P < 0.01), CRP (P < 0.01), and IL-6 (P < 0.01) levels, WBC counts (P < 0.01), and I/T ratio (P = 0.05) than the noninfection group." (PMID 22685675, 2012). "We therefore first determined the levels of a panel of markers (IL-1β, IL-6, IL-8, IL-10, IL-12p70, TNF, RANTES, MIG, MCP-1, IP-10, IFN-α, IFN-γ, Ang-1, Ang-2, uPAR and VEGF R1/Flt1) in the plasmas of 79 women who remained infection-free from inclusion through to delivery." (PMID 23155405, 2012). "Acute CVB3 infection leads to a robust inflammation in cardiac tissue of wildtype mice, which is demonstrated by high numbers of infiltrated inflammatory cells and highly increased expression of proinflammatory cytokines such as IL-1β, IL-6, and TNF-α 10 days after infection." (PMID 22675647, 2012). "Elicited macrophages from both CD200R1+/+ and CD200R1−/− mice were infected with HSV-1 (multiplicity of infection; MOI = 10), or challenged with Pam2CSK4 (100 ng/ml), or LPS (100 ng/ml), and levels of IL-6, CCL5 (Rantes), or CCL2 (MCP-1) were measured at 24, 48, and 72 h." (PMID 23082204, 2012). "On another hand, MVA modulates host immune responses after infection of immature human monocyte-derived dendritic cells by increasing IL-12, IFN-β, TNF-α and IL-6 levels, and Toll-like receptor pathways tending to induce specific CD8+ T cell and strong humoral responses." (PMID 22514660, 2012). "On admission, there was a statistically positive significant correlation between the IL-6 and the presence of infection regardless of its type (P = 0.038)." (PMID 23724320, 2012). "Further, the unchanged systemic concentrations of IL-6, KC, and IL-10 do not rule out that other important mediators in the posttraumatic inflammatory cascade may be altered by inhalative IL-10 and thereby the susceptibility to infection may again be increased." (PMID 22046081, 2012). "Our findings suggest that IL-6 does not play an essential non-redundant role in the host response to H1N1pdm infection in mice." (PMID 22679491, 2012). "Inflammation is a rapid and non-specific host defense mechanism against infection that is tightly regulated by a network of inflammatory mediators, which includes cytokines such as interleukin-6 (IL-6)." (PMID 22679491, 2012). "In contrast, while Il6 and Mmp9 were significantly highly expressed in HN878-infected cells at both time points, the level of expression of Cd209g was similar at 6 hours and higher in HN878-infected BMM at 24 hours of infection." (PMID 22280836, 2012). "Contrary to the early expression pattern of IL-6 and MCP-1, TNFα expression was extended for a few more days, thus overlapping with monocyte recruitment to the infection sites, suggesting that monocytes may contribute to TNFα production as well." (PMID 22496642, 2012). "Depletion of pDCs in these FLT3L treated mice resulted in reduced inflammation and BALF cell counts 3 days after infection, as well as a significant reduction in IL-12p40, IFN-γ, and IL-6 concentrations in both the BALF and lung homogenates after pDC depletion." (PMID 23119083, 2012). "When peripheral infection was analysed in a similar way, with a cutoff for IL-6 at 30 pg/mL, the odds ratio was not significant for any of the analyses." (PMID 23176037, 2012).